NCF1 (neutrophil cytosolic factor 1)
Diseases named in the same sentence as NCF1 in open-access papers (continued):
Sharing a sentence is not in itself a finding about the gene and the disease.
autoimmune disease (continued). "A single-nucleotide polymorphism of neutrophil cytosolic factor 1 (Ncf1), leading to an impaired generation of reactive oxygen species (ROS), is a causative genetic factor for autoimmune disease." (PMID 34257370, 2021). "Polymorphism of Ncf1 is a major factor associated with autoimmune diseases, most likely through peroxide regulatory effects." (PMID 32276661, 2020). "A more recent discovery shows that the polymorphism of the neutrophil cytosolic factor 1 (Ncf1) gene is a major genetic factor in animal models of autoimmune diseases." (PMID 32448385, 2020). "Defects in NCF1 lead to lower production of reactive oxygen species (ROS) associated with autoimmune diseases in humans." (PMID 26528554, 2015). "A mutation of Ncf1 in the mouse (Ncf1m1J), which causes production of a truncated deficient protein, has been widely used to demonstrate the role of NCF1 in the control of autoimmune disease models." (PMID 38547647, 2024). "Of note, the NCF1 His90 variant might contribute to different autoimmune diseases via different mechanisms, e.g., impairment of apoptotic cell clearance likely contributes to SLE." (PMID 36009308, 2022). "Taken together, allele frequencies of GTF2I rs117026326 and NCF1 rs201802880 polymorphisms are population dependent, with higher frequencies in East Asian populations than in others, which explains the strong association of the GTF2I-NCF1 locus with autoimmune diseases in China, Korea, and Japan." (PMID 36009308, 2022). "In addition, given that susceptibility polymorphisms may impact the treatment of disease, it is interesting to explore the association of NCF1 His90 variant with response to treatment in autoimmune diseases." (PMID 36009308, 2022). "However, this is only a preliminary association study, and further research is required into the specific mechanisms by which the NCF1-339 variant leads to maternal autoimmune disorders and immune imbalances at the maternal–fetal interface, to confirm the association with miscarriage." (PMID 36448060, 2022). "The perspective on redox regulation of T cell-mediated autoimmune diseases has shifted after the positional cloning of NCF1 SNPs in both experimental animal models and humans." (PMID 38671946, 2024). "Second, NCF1 p.R90H has been found to be closely related with a variety of autoimmune diseases including SLE, RA, SS, and others." (PMID 35788118, 2022). "Neutrophil cytoplasmic factor 1/2/4 (NCF1/2/4) belongs to the NADPH oxidase complex, which is a cytoplasmic component, and its polymorphism is the main factor related to autoimmune diseases, which is probably caused by the regulation of peroxide." (PMID 34708124, 2021). "In mice, collagen induced arthritis (CIA) and psoriatic arthritis are autoimmune disorders known to be regulated by Ncf1, and they were utilized in the present study to compare the Ncf1 knockout with Ncf1m1J mice." (PMID 26528554, 2015). "Ncf1, a gene important for oxidative burst formation, regulates the severity of other autoimmune diseases and modulates (in-)directly the level of T-cell dependent autoimmune responses." (PMID 17052335, 2006). "The first autoimmune disease-associated gene cloned was the neutrophil cytosolic factor (Ncf1), encoding a protein (NCF1, alias p47phox) critically involved in the formation of the NADPH oxidase 2 (NOX2) complex, responsible for inducing reactive oxygen species (ROS) responses." (PMID 39939342, 2025). "Furthermore, some of these genes have been associated with susceptibility to the development of autoimmune diseases—JAK2, BACH2, and NCF1." (PMID 39598118, 2024). "In accordance with these findings, NCF1 variants that reduce NOX2-derived ROS production in rat and mice have also been shown to promote multiple experimental autoimmune diseases, such as pristane-induced arthritis, experimental autoimmune encephalomyelitis, and SLE-like disease." (PMID 36009308, 2022).
autoimmune disease (continued). "It is interesting that the enhancement of the Th1 response due to Ncf1 deficiency contributes to regulate the type 2 allergic inflammation, since a stronger Th1 response seems to be closely related to the disease-promoting effect of Ncf1 in autoimmune diseases." (PMID 34970267, 2021). "Whether the ΔGT/GTGT ratio has functional significance in terms of individual NCF1 expression, ROI production or susceptibility to infectious or autoimmune diseases is currently unknown." (PMID 19077231, 2008). "Recently, a major single nucleotide variant on the NCF1 gene, leading to an amino acid replacement from arginine to histidine at position 90 (NCF1R90H), associated with low production of reactive oxygen species (ROS), was found to be causative for several autoimmune diseases." (PMID 37507888, 2023). "Hence, it suggested that NCF1 p.R90H might be involved in the pathogenesis of autoimmune diseases through disturbance of ROS homeostasis in pDCs and alteration of IFN-I production." (PMID 35788118, 2022). "In addition, neutrophil cytosolic factor 1 (NCF1, rs201802880, major/minor alleles: A/G, amino acid substitution: C to T from arginine to histidine) of the NOX2 complex (also known as p47PHOX), which is essential for ROS initiation, has been shown to play an important role in autoimmune diseases." (PMID 34831240, 2021). "Therefore, the Ncf1 gene has a more general effect on T cell-dependent autoimmune diseases." (PMID 32380695, 2020). "Susceptibility to animal models of autoimmune diseases such as collagen-induced arthritis (CIA), experimental autoimmune neuritis (EAN) and experimental autoimmune encephalomyelitis (EAE) is influenced by genetic variation of Ncf1 (p47phox), another NADPH-oxidase subunit." (PMID 19077231, 2008). "Most genes were related to autoimmune diseases like ATM, NCF1, MCM4, FCN3, and DOCK8 or autoinflammatory diseases associated with the release of IFN-gamma, such as PRF1, NOD2, and MEF." (PMID 37588055, 2023). "In addition, since NOX2-derived ROS play an important role in autophagy and aberrations of autophagy has been observed in autoimmune diseases, such as SLE, a potential mechanism underlying hypoactive NCF1 variant-caused autoimmune conditions might be regulating the homeostasis of autophagy." (PMID 36009308, 2022). "Taken together, our experiments indicate that LAT is redox-regulated, interacting with NCF1/NOX2 complexes, and may therefore be a key target for understanding and intervening in the treatment of RA and other autoimmune diseases." (PMID 38671946, 2024).
diabetes (22 papers, 2010 to 2025). "Cat, Sod1, Sod2, Prkca, and Nos1 expression levels were decreased, while Ncf1, Xdh, and Cyba expression levels were increased in diabetes." (PMID 20979611, 2010). "A retrospective study done at the NIH on patients with CGD reported the incidence of diabetes as 9.4%, primarily in NCF1 deficiency regardless of the mutation or residual superoxide activity." (PMID 38022624, 2023). "Pre-clinical studies have noted that NADPH oxidase 2 deficient mouse models carrying non-functional allele of either Cybb (gp91phox) or Ncf1 are resistant to diabetes development and exhibit enhanced insulin secretion in response to glucose." (PMID 31118934, 2019).
atherosclerosis (20 papers, 2008 to 2025). A disease characterized by the build-up of fatty material and calcium deposition in the arterial wall resulting in partial or complete occlusion of the arterial lumen. "Deletion of p47phox (NCF1) in the ApoE knockout mouse model of atherosclerosis reduces aortic ROS levels and shrinks plaque size." (PMID 40710296, 2025). "Then, KEGG pathway analysis revealed that these genes were enriched in “lipid and atherosclerosis” (Ncf1, Eif2s1, Tank, Vav1, Nfe2l2), “B-cell receptor signaling pathway” (Blnk, Dapp1, Vav1), and “Fc gamma R-mediated phagocytosis” (Prkcg, Ncf1, Vav1)." (PMID 38952478, 2024). "Previous studies have demonstrated that macrophage-derived MMP9 promotes the infiltration of monocyte/macrophages into the lesions thereby enhancing atherosclerosis and NCF1 expression leads to priming of human macrophage oxidative burst." (PMID 36035208, 2022).
Autoimmunity (19 papers, 2007 to 2025). The occurrence of an immune reaction against the organism's own cells or tissues. "Recently, a missense SNP variation in NCF1 was found to be associated with several autoimmune conditions." (PMID 30323221, 2018). "The present study describes for the first time a direct comparison of these two different Ncf1-defective alleles, with all other factors neutralized, in the development of autoimmunity and inflammation." (PMID 26528554, 2015). "An apparent predisposition to autoimmunity in Ncf1−/− mice is similar to the findings in human CGD patients." (PMID 21253614, 2011). "Reduced ROS production due to NCF1 variants is linked to autoimmunity in diseases like SLE." (PMID 39796280, 2025). "Taken together, the hypoactive NCF1 variant might contribute to T cell autoimmunity by promoting autoreactive T helpers and inhibiting the induction of Tregs." (PMID 36009308, 2022). "The NCF1 p.R90H mutation interrupts the negative regulation and leads to autoimmunity." (PMID 35788118, 2022). "Experimental and clinical evidence suggests that the hypoactive NCF1 His90 variant might contribute to autoimmune conditions via multiple pathways, including impairing apoptotic cell clearance, regulating the formation of N." (PMID 36009308, 2022). "Animal studies have shown that NCF1-mutated mice show an increase of T cell–dependent autoimmunity." (PMID 33903979, 2021). "Since genetically controlled mice with a point-mutation in the Ncf1 gene are susceptible to chronic inflammation and autoimmunity, we tested whether they presented increased predisposition to develop chronic colitis." (PMID 24873968, 2014). "The causal NCF1 His90 variant leads to an impaired NOX2 activity and confers a risk for various autoimmune conditions." (PMID 36009308, 2022). "Down-regulation of NCF1 reduces cytokine production, thus, playing an essential role in modulating autoimmunity, immunologic processes, inflammation, proliferative responses and apoptosis." (PMID 31694290, 2019). "Since Ncf1 regulates auto-reactive T cells through APCs in autoimmunity, we further investigated activated T cells and DCs." (PMID 27829407, 2016). "For example, Ncf1 congenic studies have revealed an unexpected, protective role of ROS in autoimmunity." (PMID 27736747, 2016). "One of the strongest genetic associations with autoimmune arthritis in animal models of the disease is the gene Ncf1 that, when deleted, leads to low ROS production and autoimmunity." (PMID 21253614, 2011). "Homozygosity for p.Arg90His in NCF1 should be considered contributory in young patients with an atypical systemic inflammatory antecedent phenotype that may evolve into autoimmunity later in life." (PMID 33892719, 2021). "The p.Arg90His substitution in NCF1 encoding the p47phox subunit of the phagocyte NADPH oxidase was reported to cause the reduction of reactive oxygen species in patients with SLE and other autoimmune conditions including primary Sjögren’s syndrome and rheumatoid arthritis (RA)." (PMID 31575058, 2019). "Since disruption of PAD4 - NADPH oxidase association by citrullination abolishes ROS production, this raises the possibility that NCF1 SNP variants may also impact PAD4 interaction, reduce NADPH oxidase activity and influence autoimmunity." (PMID 30323221, 2018). "Our current understanding of the role of Ncf1 in autoimmunity has recently been reviewed." (PMID 27736747, 2016). "Our observations indicate that there is some remaining suppressive function, apparently related to TGFβ, that is displayed during the interaction of Ncf1−/− Tregs and Ncf1−/− Teff and perhaps this may serve as an explanation for mild to moderate degree of autoimmunity in Ncf1−/− mice." (PMID 21253614, 2011). "In conclusion, we show that PTPN22 functionally interacts with Ncf1 and is regulated by oxidation via the noncatalytic C129 residue and oxidation-prone PTPN22 leads to increased severity in the development of T-cell-dependent autoimmunity." (PMID 35587260, 2022).
rheumatoid arthritis (18 papers, 2012 to 2025). A chronic, systemic autoimmune disorder characterized by inflammation in the synovial membranes and articular surfaces. "In rodents, a seminal paper by the team of Rikard Holmdahl demonstrated that a loss of function polymorphism in the Ncf1 gene—which codes for the p47phox subunit of NOX2—is a main driver of experimental rheumatoid arthritis." (PMID 30050527, 2018). "Importantly, it is known that copy number variation of the NCF1 gene is associated with rheumatoid arthritis and a NCF1 single-nucleotide polymorphism represents the major genetic factor associated with systemic lupus erythematosus." (PMID 35551269, 2022). "Previous evidence has demonstrated that mutations in NCF1 and NCF2 may cause granulomatous disease, and the copy number variation of NCF1 is associated with rheumatoid arthritis." (PMID 27878450, 2017). "The NCF1 gene copy number has been associated with human rheumatoid arthritis (RA)." (PMID 26528554, 2015). "In addition, several studies have established a strong correlation between NCF1 and renal fibrosis as well as rheumatoid arthritis." (PMID 39544234, 2024). "In this study, we employed bioinformatics and machine learning techniques to identify seven key genes associated with rheumatoid arthritis (RA): AKR1B10, MMP13, FABP4, NCF1, SPP1, COL1A1, and RASGRP1." (PMID 39430588, 2024). "In 2017, two studies reported that a missense mutation in neutrophil cytosolic factor 1 (NCF1) within the locus is associated with SLE, pSS and rheumatoid arthritis (RA)." (PMID 36009308, 2022).
colitis (16 papers, 2013 to 2025). Inflammation of the colon. "Studies in NCF1−/− mice revealed that p47phox deficiency resulted in increased susceptibility to colitis in a manner that was directly influenced by the microbiome." (PMID 40710296, 2025). "Weight loss began on day 3 after DSS colitis induction with all DSS-treated animals reaching the minimum weight on day 13 (i.e., during the recovery period) and with Ncf1 mice presenting a greater weight loss than WT mice." (PMID 29867918, 2018). "Colitis was induced in Ncf1-mutant and wild-type mice by a 1st 7-days cycle of dextran sulfate sodium (DSS), intercalated by a 7-days resting period followed by a 2nd 7-days DSS-cycle." (PMID 24873968, 2014). "This severe colitis in Ncf1* mice was mediated by increased local production of peroxynitrites, pro-inflammatory cytokines and phosphorylated LRRK2." (PMID 24873968, 2014). "This Ncf1* colitis is characterized by the presence of inflammatory cells without epithelioid granulomata, and with dysplasia often with the criteria of severe dysplasia and intra-epithelial adenocarcinoma, in particular in the transversal region of the colon." (PMID 24873968, 2014). "In our DSS-induced colitis model we observe that between D14 and D21 Ncf1* mice had a higher IFN-γ expression in the colon mucosa, which was paralleled by a higher expression of pLRRK2." (PMID 24873968, 2014). "Therefore, in the present study, B10.Q/Ncf1 mice were used to develop a new model of inflammation-driven colon carcinoma by induction of colitis with DSS and address the putative role of ROS in tumor formation and systemic metabolic alterations." (PMID 29867918, 2018). "Thus, the clinical symptoms and histopathologic signs we observed in Ncf1* mice point towards a severe DSS-induced colitis." (PMID 24873968, 2014). "Colitis induction with DSS led to a reduction in the colon length in both the WT and the Ncf1 mice resulting in a significant shortening of the colon after a second induction period." (PMID 29867918, 2018). "Colitis was induced with dextran sulfate sodium (DSS) supplied via the drinking water in wild-type (WT) and Ncf1-mutant (Ncf1) B10.Q mice using two different protocols, one mimicking recovery after acute colitis and another simulating chronic colitis." (PMID 29867918, 2018). "Contrasting to the studies on Ncf1−/− and gp91phox−/− mice, when DSS-colitis was induced in p40phox−/− mice the colon tissue was more injured in the mice deficient of ROS production than in the control group." (PMID 24873968, 2014). "In the present study, we show, for the first time, that Ncf1* treated with repeated DSS-cycles intercalated by a resting period develop an earlier and severer colitis, contrasting to the milder colitis developed by oxidative-burst competent wild-type animals." (PMID 24873968, 2014). "In our study, the lack of inflammatory-derived ROS on Ncf1 DSS-induced colitis model was sufficient to develop adenocarcinoma and exhibit a different blood plasma lipid profile." (PMID 29867918, 2018). "The lack of capacity of NOX2 to generate oxidative burst in the Ncf1 model enhanced the DSS-induced colitis symptoms as far as cancer onset." (PMID 29867918, 2018). "NCF1-knock-out mice have increased leukocyte infiltration and morphological changes in the colonic mucosa, indicating that the absence of the NCF1 gene could aggravate colitis." (PMID 35923697, 2022). "Additionally, the diagnosis of NCF1-CGD in older children and adults is not uncommon; adult cases have been diagnosed presenting with pneumonia or in the setting of colitis." (PMID 40934010, 2025).
Hyperglycemia (15 papers, 2010 to 2026). An increased concentration of glucose in the blood. "Polymorphisms in CYBB (NOX2), NCF1 (p47phox), and NCF2 (p67phox) may differ from Caucasian or Asian populations, potentially modulating basal NOX2 activity and response to hyperglycemia." (PMID 41607455, 2026). "In contrast, nicotine further increased the hyperglycemia-induced expression of Ncf1." (PMID 37415117, 2023).